VSTM1 (V-set and transmembrane domain containing 1)
Description:
[Isoform 2]: Behaves as a cytokine, promoting IL17A secretion by CD4+ T-cells, and differentiation and activation of IL17 producing helper T-cells (TH17). [Isoform 1]: Inhibitory immune receptor involved in the regulation of phagocytes.
Synonyms: SIRL-1; UNQ3033; SIRL1
Tractability: Antibody: UniProt places it where antibodies can reach, with high confidence; UniProt predicts a signal peptide or a membrane-spanning region; its Gene Ontology location is reachable by antibodies, with medium confidence.
Gene: Protein-coding gene on chromosome 19 (54,040,825 to 54,063,953, reverse strand). Ensembl gene ENSG00000189068.
Subcellular location: Membrane (Isoform 1); Secreted (Isoform 2)
Subcellular location (Human Protein Atlas): Vesicles; Predicted to be secreted
Gene Ontology:
Molecular function: transmembrane signaling receptor activity
Biological process: signal transduction
Cellular component: plasma membrane; extracellular region; membrane
Genetic constraint (gnomAD): Loss-of-function variants: 28 observed, 36.8 expected, observed/expected ratio (o/e) 0.76, 90% interval 0.56 to 1.04. The upper end of that interval is the gene's LOEUF score, 1.04, which puts it in group 4 of 6, group 1 being the genes least tolerant of losing a copy. Missense variants: 304 observed, 303.22 expected, observed/expected ratio (o/e) 1, 90% interval 0.91 to 1.1. Synonymous variants: 115 observed, 115.29 expected, observed/expected ratio (o/e) 1, 90% interval 0.86 to 1.16.
Homologues: Orthologues: chimpanzee VSTM1 (98% identical), macaque VSTM1 (87% identical), pig VSTM1 (58% identical), dog VSTM1 (36% identical). Paralogues in human: TARM1 (32% identical), LILRB5 (29% identical), LILRB1 (28% identical), LILRA4 (28% identical), LILRA6 (28% identical), LILRB3 (28% identical), LILRA1 (27% identical), LILRA2 (27% identical), LILRB2 (26% identical), GP6 (25% identical), LILRA5 (24% identical), NCR1 (23% identical), and 13 more.
Diseases named in the same sentence as VSTM1 in open-access papers:
VSTM1 is named in the same sentence as 20 diseases in open-access papers, as found by Europe PMC text mining. Sharing a sentence is not in itself a finding about the gene and the disease. The quoted sentences say what the papers report.
leukemia (3 papers, 2015 to 2022). A malignant (clonal) hematologic disorder, involving hematopoietic stem cells and characterized by the presence of primitive or atypical myeloid or lymphoid cells in the bone marrow and the blood. "Downregulated in bone marrow cells from leukemia patients, VSTM1 may become a diagnostic and treatment target." (PMID 35962453, 2022). "VSTM1 (V-set and transmembrane domain-containing 1) encodes a potential leukocyte differentiation antigen that is highly expressed in myeloid cells, but silenced in multiple leukemia cell lines." (PMID 25887911, 2015). "We measured VSTM1 expression in leukemia cell lines and bone marrow biopsies from leukemia patients using qRT-PCR." (PMID 25887911, 2015). "Herein, we report a potential leukocyte differentiation antigen gene VSTM1 (V-set and transmembrane domain-containing 1) that was downregulated in bone marrow cells from leukemia patients and exhibited a higher degree of promoter methylation." (PMID 25887911, 2015). "Therefore, VSTM1-v1 might represent an important myeloid leukocyte differentiation antigen and provide a potential target for the diagnosis and treatment of leukemia." (PMID 25887911, 2015).
rheumatoid arthritis (3 papers, 2016 to 2025). A chronic, systemic autoimmune disorder characterized by inflammation in the synovial membranes and articular surfaces. "Genes PACRG and VSTM1 were reported to be involved in the Parkinson and rheumatoid arthritis, respectively." (PMID 35568907, 2022). "The role of VSTM1 in autoimmune diseases is primarily investigated through its role in regulating ROS production and NET formation in autoimmune diseases, such as systemic lupus erythematosus (SLE) and rheumatoid arthritis (RA)." (PMID 39989259, 2025).
autoimmune disorders (1 paper, 2025). "Whether aberrant VSTM1 function serves as a predisposing factor for autoimmune diseases or whether it is a result of sustained inflammation within autoimmune conditions remains unclear." (PMID 39989259, 2025). "VSTM1 is involved in various pathological conditions, including autoimmune disorders and cancer, and its restricted expression on myeloid cells highlights its potential as a specific therapeutic target." (PMID 39989259, 2025). "In disease, VSTM1 is differentially expressed and might play a role in various autoimmune diseases and cancer." (PMID 39989259, 2025).
lung carcinoma (1 paper, 2025). "In advanced‐stage lung cancer, VSTM1 expression on tumor‐associated myeloid cells was increased compared with early‐stage lung cancer, suggesting VSTM1 expression on myeloid cells increases during tumor development." (PMID 39989259, 2025).
Obesity (1 paper, 2022). Accumulation of substantial excess body fat. "For those 12 genes, six of them (DDO, SEPT9, TMEM45B, RXRα, ZNF395 and AHRR) were previously reported to be implicated in the obesity or related diseases and the rest six were novel (PACRG, LINC00494, KLHL4, DTX1, VCX3A and VSTM1)." (PMID 35568907, 2022).
pneumonia (1 paper, 2021). An acute, acute and chronic, or chronic inflammation focally or diffusely affecting the lung parenchyma, caused by an infection in one or both of the lungs (by bacteria, viruses, fungi, or mycoplasma.). "In patients with pneumonia, the individuals with high expression of VSTM1 in neutrophils suffer more serious clinical symptoms than those with low expression of VSTM1." (PMID 34712823, 2021).
sleep apnoea (1 paper, 2021). "Similarly, we find new evidence that serum VSTM1 is causally associated with sleep apnoea (Padj = 2.03 × 10−2)." (PMID 34857772, 2021).
infection (2 papers, 2021 to 2025). The state of being infected such as from the introduction of a foreign agent such as serum, vaccine, antigenic substance or organism. "In patients with RSV or COVID‐19 infection, soluble VSTM1 is increased in sputum compared with plasma, suggesting that VSTM1 is shed from the cell surface during infection." (PMID 39989259, 2025). "Compared with the control group (9.62 ± 1.98) and NC group (10.18 ± 2.02), the proportion of apoptotic and necrotic cells after infection with VSTM1 overexpression virus was obviously increased (36.95 ± 2.59) compared with the NC group (n = 6, p < 0.0001)." (PMID 34712823, 2021).
tumor (1 paper, 2025). "Downregulation of VSTM1 thus seems favorable for a hematopoietic tumor cell, the mechanism of which is still unclear." (PMID 39989259, 2025).
VSTM1 also shares sentences with these, for which no sentence is quoted: cancer (2 papers); gout (2); atopic dermatitis (1); Crohn disease (1); dermatitis (1); dyskeratosis congenita (1); inflammatory bowel disease (1); inflammatory skin disease (1); lymphoma (1); Sepsis (1); systemic lupus erythematosus (1).